IL17A (interleukin 17A)
Diseases named in the same sentence as IL17A in open-access papers (continued):
Sharing a sentence is not in itself a finding about the gene and the disease.
tumor (continued). "In addition, high levels of TGF-β and IL-17A were detected in tumor tissues rather than in normal mucosa." (PMID 22994684, 2012). "Similarly, IL-17A promoted tumor angiogenesis in vivo but failed to exhibit any mitogenic activity for HUVECs in vitro; it regulated the production of VEGF depending on cell types in vitro." (PMID 22509371, 2012). "In the AOM/DSS-induced murine CAC model, Th17-related cytokines, including IL-17A, IL-21, IL-22, TNF-α, and IL-6, are produced by tumor-infiltrating lymphocytes (TIL), which could activate the STAT3/NF-κB pathway, thereby promoting CAC cell proliferation and accelerating tumor progression." (PMID 40109347, 2025). "This suggests that IL-17A may inhibit the occurrence and development of LUAD by suppressing the oxidative stress and inflammatory responses involving Ferulic acid 4-sulfate-related genes and by affecting the extracellular matrix and cell junctions, thereby reshaping the tumor microenvironment." (PMID 39257908, 2024). "Importantly, IL-17A inhibition did not compromise the anti-tumor efficacy of ICI treatment." (PMID 37445704, 2023). "In particular, oestrogens may favour an immunosuppressive TME by enhancing Th2 responses, tumour-promoting cytokines (IL-4, IL-6, IL-17A and TNF) and M2 TAM infiltrations, unlike M1 TAM infiltration and Th1 responses, which are commonly joined with Th1 cytokines (IL-12 and IFN)." (PMID 38332913, 2023). "IL17A, although not changing overall GvHD and graft versus tumor (GVT) activity, contributes to the early development of CD4‐mediated GvHD by promoting the production of proinflammatory cytokines and might have contributed to the bodyweight loss in the early phase after aGvHD induction." (PMID 36051085, 2022). "Notably, application of the anti-IL17A mAb, anti-PD-1 mAb or anti-Ly6G mAb alone may not be sufficient for tumor growth inhibition." (PMID 34721375, 2021). "Additional studies are warranted to investigate whether RORγ activators or a low dose of IL-17A can be used for boosting clinical response to neoadjuvant chemotherapy or PD-1 blockade treatment in patients who have a “cold tumor” and normally do not respond to these treatments." (PMID 32770025, 2020). "However, anti-IL-17A Ab treatment did not prolong the survival time of tumor-bearing mice." (PMID 27935862, 2017). "However, there was no change in the number of tumor-derived CD4+IL17A+ (Th17) cells." (PMID 27075020, 2016). "However, there were no reports concerning the effect of IL-17A on tumor infiltrating B cells." (PMID 26942702, 2016). "We hypothesized that IL-17A produced locally in tumor microenvironment might have an important role on tumor growth via angiogenesis and tumor immunity, thereby tumor development might be suppressed by inhibiting IL-17A at tumor local sites but not systemically." (PMID 23372655, 2013). "IL-17A-positive cells could be detected in both tumor and adjacent non-tumorous tissues." (PMID 21760911, 2011). "Collectively, our observations demonstrate the modest IL-17A increase after RS, which may enhance antimicrobial defense and wound healing, while stable proangiogenic factor levels suggest restrained angiogenic activity, potentially supporting recovery without promoting tumor growth." (PMID 41155334, 2025). "Macrophages and tumor cells expressed much high levels of VEGF compared with TANs, while levels of IL-17A were not higher." (PMID 38329810, 2024). "Therefore, neutralizing IL-17A could recover the interaction of effector CD8+ T cells and tumor vascular endothelium via the LFA-1/ICAM-1, and also restore the NO production from endothelial cells, facilitating the infiltration of CD8+ T cells, particularly the stem-like subset, into the tumor bed." (PMID 37605139, 2023).
tumor (continued). "Interestingly, Rag1-knockout mice models lacking in mature B and T lymphocytes and anti-IL17a antibody-treated mice derived no benefits from antibiotics, ruling out the possibility that antibiotics play a direct beneficial role and suggesting an immune-mediated tumor attenuation." (PMID 37370753, 2023). "In this study, we reveal that a higher accumulation of tumor-infiltrating CD39+γδ Tregs in RSCRC compared with paired normal tissue and LSCRC, along with increased production of IL-17A and adenosine, enhanced the immunosuppressive function." (PMID 34283812, 2021). "We have recently developed a PDAC mouse model lacking the IL17A gene, and we observed a unique TME that efficiently supported the anti-tumor response induced by an anti-tumoral vaccine." (PMID 33802061, 2021). "The pro-tumor properties of IL-17A and PDL1 in various cancers have been previously examined; however, the relationship and roles of IL-17A and PDL1 in ER-negative breast cancer have not been evaluated." (PMID 27935862, 2017). "We observed significantly higher tumor and splenic CD4+ T cell–derived IL17A production in the IL-10−/− B16/F10 mice but not in the TDLN (data not shown)." (PMID 27075020, 2016). "The result showed that IL-17A expression did not correlate to patients’ age, FIGO stage, and tumor size, while IL-17A expression was significantly correlated to patients’ invasion depth and lymphatic metastasis status (P<0.01, students t-test)." (PMID 25250801, 2014). "Although the potential underlying mechanisms are not identified yet, it has been reported that several tumor types, including lung tumors, are able to produce considerable amounts of certain cytokines such as TGF-β, IL-10, or IL-17A." (PMID 22855687, 2012). "To predict and validate the interactions of YKL-40 in the tumor microenvironment, we analyzed mRNA expression of YKL-40, IL-17A, PD-L1, and MMP-8 in 136 samples of CRC tissue and non-cancerous colonic tissue obtained from Gene Expression Omnibus (GEO) datasets GDS4382, GDS4513, and GDS4515." (PMID 37185706, 2023). "IL-33/ST2 signaling suppresses IL-17A production and potentially promotes the conversion of IL-17-producing CD4+ T cell types to IL-17-negative (RORγt−) ST2+ FOXP3+ Treg cells, modifying the inflammatory signals within the tumour microenvironment to promote CRC." (PMID 36569832, 2022). "Furthermore, it was found that tumor resident γδ T cells were not IFN-γ producers and their major functions involved IL-17A production and neutrophil infiltration and recruitment." (PMID 33375062, 2020). "In contrast, IL-17A and TNF secretion by TCRγδCD8− T cells is not affected by Treg depletion and could counteract the CD8αβ T cell-mediated anti-tumor response." (PMID 32185408, 2020). "Again, we were not able to detect significant changes for IL-17A, indicating that TH17 cells may not play a significant role in the delayed tumor growth of animals receiving a HSD." (PMID 31214164, 2019). "Furthermore, as for the promoting effects of IL‐17A on GC in our studies, IL‐17A induction may have negative impacts on anti‐tumor immune responses, and the impacts of B7‐H2 ligation to ICOS on Tregs in tumor immunosurveillance need further investigation." (PMID 34185422, 2021). "To verify the role of IL-17A/STAT3 signaling on CD8+ T cell migration and tumor progression in vivo, we used immune-cell-infused xenograft mouse model according to previous studies, which may not represent tumor immunity." (PMID 32503584, 2020). "In the present study, the absence of STAT1 significantly increased the production of Th17 cytokines (IL-17A, IL-17F, and IL-22) but not of TNF-α and IFN-γ, indicating that a lack of STAT1 signaling induces a significant change in the microenvironment that supports inflammation and tumor formation." (PMID 30235866, 2018).
tumor (continued). "Indeed, transfer of IL-17A−/− Th17 cells, IFN-γ−/− Th17 cells, and Tbx21−/− Th17 cells into WT mice or transfer of WT Th17 cells into IFN-γ-R−/− recipient mice failed to control tumor growth." (PMID 26583099, 2015). "According to whether the frequency of IL-17A-positive cells was above the mean level (341 cells) in tumor tissue or not, HCC cases in the present study were divided into two groups: IL-17A-high group (above the mean level, n = 15) and IL-17A-low group (below the mean level, n = 28)." (PMID 21760911, 2011).
infection (2,272 papers, 2007 to 2026). The state of being infected such as from the introduction of a foreign agent such as serum, vaccine, antigenic substance or organism. "This protection required type III secretion system effector-mediated epithelial injury during primary infection and was associated with sustained IL-17A signalling, which contributed to the protective phenotype." (PMID 42269772, 2026). "A meta-analysis involving 2967 individuals in Colombia, Argentina, Bolivia, and Brazil indicated that IL17A rs4711998 was associated with infection." (PMID 40297326, 2025). "The variant rs8193036, located in the IL17A gene, was associated with infection and CCC development in a Colombian cohort, while IL17A rs763780 was associated with T. cruzi infection in a Brazilian cohort." (PMID 40297326, 2025). "IRF4-deficient mice exhibit reduced NKp46+ ILC3s, expanded precursor-like NKp46−CCR6− ILC3s, and impaired interleukin-22 (IL-22)/IL-17A production, increasing susceptibility to infections." (PMID 40585371, 2025). "In the context of T. gondii infection, Th17 axis was shown to be crucial in controlling infection and mortality in mice, as IL-17A-deficient C57BL/6 mice displayed higher mortality followed by exacerbated levels of IFN-γ." (PMID 40223760, 2025). "After identifying Vγ4+ γδ T cells as a key source of IL-17A in the M. pachydermatis-associated skin, we assessed the consequences of γδ T cell deficiency on infection dynamics and the overall antifungal response." (PMID 38215167, 2024). "Accordingly, global IFNLR1-/- mice had significantly increased IL-17 and IL-22 in the airways, and neutralization of IL-17A during infection caused significantly increased bacterial burden compared to untreated mice." (PMID 39178311, 2024). "CD30L/CD30 signaling pathways are crucial for the maintenance and activation of naturally occurring IL-17A-producing γδ T cells in mucosa-associated tissues and thus control the infection." (PMID 38339023, 2024). "Pro-inflammatory cytokines such as IL-6, tissue necrosis factor (TNF), and IL-17A are necessary for initiating an effective inflammatory process against infection and they are associated with multiple-system organ failure and mortality." (PMID 38969796, 2024). "Among immune cells or cytokines associated with active protection against infection, IL-17A levels inversely correlated with H. pylori load in the gastric mucosa, suggesting a role of IL-17–secreting cells in eradicating acute H. pylori infection." (PMID 36810249, 2023). "In a neonatal mouse model of influenza, infection-induced IL-17A was associated with increased IL-33 production by lung epithelial cells, subsequently generating a local type 2 immune response." (PMID 37783278, 2023). "Strikingly, we found that Vγ4/6−/− mice do not lose subcutaneous adipose tissue to the same extent as wild type controls during infection, mirroring our previous studies where we proposed IL-17A as a driver of infection-associated adipose tissue wasting." (PMID 37644007, 2023). "In mammals, T cells of the γδ subset immediately produce IL-17A and induce inflammation upon pathogenic infections." (PMID 37631976, 2023). "In line with this, the type III cytokines Il17a, Il17f and Il22, which are all critical for maintaining intestinal homeostasis and immunity to upcoming pathogenic infections, were significantly downregulated after the first switch to FD." (PMID 37580603, 2023). "IL-17A is a hallmark factor secreted by Th17 cells, and it can effectively mediate the inflammatory response during early infection or injury." (PMID 37111225, 2023). "Genetic deletion of RELMα obviously alleviates infection-induced colitis in mice and shows the deficiency of IL-23p19 in macrophages as well as the decrease of IL-17A in CD4+ T cells." (PMID 36691020, 2023).
infection (continued). "Depletion of CD4+ Th cells from PBMCs isolated on day 7 after infection resulted in almost complete loss of IL-17A production in response to stimulation with dmLT and LTB, supporting that the IL-17A responses to LT were derived from CD4+ Th cells." (PMID 37809062, 2023). "Specifically, the infection of C. albicans caused the activation of the IL-17A/IL-17RA signaling pathway in OC cells." (PMID 37067414, 2023). "IL-17A plays a key role in preventing both infection progression and associated infectious complications." (PMID 35980044, 2022). "Here, we show that after experimental infection with high doses of Mtb H37rv, IL-17A-deficient (−/−) mice exhibited high susceptibility to the infection, which was mediated by the strong accumulation of neutrophils in the infected lung tissue." (PMID 36139450, 2022). "We also found that M. intracellulare infection causes early production of IL-17A (during the 1st two weeks of infection) by T cells, especially RORγt+ T cells, which culminates in lung damage (inflammation and fibrosis) and death in chronically infected mice." (PMID 35363832, 2022). "In general, Th2 cytokines (e.g., IL-6) and Th17 cytokines (e.g., IL-17A) were associated with infection progression under conditions of compromised immunity, and the differentiation and immune function of Th17 cells was positively regulated by IL-6." (PMID 35558127, 2022). "On both days three and five after infection, there were higher percentages and numbers of ILC3s producing IL-17A in the brains of IL-10-deficient mice than WT mice." (PMID 36016413, 2022). "IL-17A is a key player in the immune system, exhibiting roles in the defense against pathogenic infections." (PMID 33879639, 2021). "When induced in IL-17a/f -/- or γδ T cells-deficient mice upon infection, lymphoid structures were less organized and, in the absence of γδ T cells, showed a reduction in number and size." (PMID 34335608, 2021). "In host defensive responses, IL-17A is mostly beneficial against infections caused by extracellular bacteria, intracellular bacteria, and fungi." (PMID 33879639, 2021). "Consistent with the data obtained from IL-17A systemic application, infection with CR/IL17 limited the body weight loss and the systemic bacterial dissemination consequent to IL-33 treatment." (PMID 33654214, 2021). "After 5 days of infection with C. albicans, real-time PCR assay showed that expression of the genes encoding Ifng, Il17a, and Il17f was attenuated in the kidneys from Trim31−/− mice compared to Trim31+/+ mice." (PMID 34362877, 2021). "Defects in bacterial clearance from the nasal mucosae during primary or secondary infections of Il17A−/− mice with B. pertussis were associated with significantly reduced recruitment of Siglec-F+ neutrophils." (PMID 33976385, 2021). "It enhances the body’s defenses against pathogens, but also increases the inflammatory damage to the body, which makes IL-17A functional in different pathogenic infections." (PMID 33879639, 2021). "Some of these genes are controlled by Dnase2, Ikbkg, Il17a, Snca, Stat2, Tlr3 and their induction is associated with suppression of infection." (PMID 32793510, 2020). "Upon infection, IL-17A production by both Gal-3-deficient and wild-type neutrophils is higher than that of CD4+ T cells and is increased by the addition of recombinant IL-23." (PMID 32973776, 2020). "As a crucial part of host immunity, IL-17A confers powerful protective effects against infections caused by bacteria, fungi, virus, and parasites;." (PMID 32849528, 2020). "So far, autoantibodies to interferon (IFN)-γ, GM-CSF, to a group of TH-17 cytokines comprising IL-17A, IL-17F, IL-22, IL-23, and to IL-6 have been found to be causative or closely associated with susceptibility to infection." (PMID 32419033, 2020). "In mammals, interleukin (IL)-17A and F are hallmark inflammatory cytokines that play key roles in protection against infection and intestinal mucosal immunity." (PMID 32256492, 2020).
infection (continued). "Overexpression of genes encoding IL-17A and IL-17F was found in the mammary tissue during infection by E. coli." (PMID 33059767, 2020). "IL-17A was beneficial during infections caused by minimally encapsulated bacteria, but significantly increased lung pathology and mortality if the infectious organism was heavily encapsulated." (PMID 31507598, 2019). "R. anatipestifer (RA) is one of the most harmful bacterial pathogens affecting the duck industry, and infection is associated with the production of proinflammatory cytokines, including IL-17A." (PMID 31519917, 2019). "This approach was validated by our identification of two pathways that were already linked to infection by Mucorales: interleukin-22 (IL-22) and IL-17A." (PMID 30108171, 2018). "In this study, we examined the association of IL-17A with C. neoformans infection by using in vivo infection model." (PMID 30409128, 2018). "Infection of mice with STm caused an upregulation of Ccl2, Tnfa, Il17a, and Ifng at all-time points investigated." (PMID 30487793, 2018). "IL-6 and IL-17A were the primary cytokines positively and significantly associated with mortality at time point 1 (2–4 days after infection) (HR 1.72, 95% CI 1.25–2.37, p = 0.001) and (HR 2.36, 95% CI 1.35–4.15, p = 0.003), respectively." (PMID 29695270, 2018). "Although over 95% of the eosinophils were found to be positive for IL-23p19 and IL-17A, only 18% and 8% of eosinophils were found to associate with conidia one and three days post-infection, respectively." (PMID 28095479, 2017). "Controlling the recruitment of neutrophils and other immune cells to the infection site is a major mechanism underlying IL-17A activities." (PMID 28377603, 2017). "At 12 h and 24 h post-infection, both E. coli and P. aeruginosa resulted in elevated ROS levels and IL-17A production under AnxA2 deficiency." (PMID 27389701, 2016). "Levels of IL-17A were increased following infection in both Balb/c and C57BL/6J mice, and this was associated with the host response to both M1 and M28 GAS." (PMID 27241677, 2016). "IL‐17A‐deficient mice showed decreased survival rates during the 1‐year observation period, and had an increased bacterial burden from day 30 of the infection when compared to wild‐type C57BL/6 mice." (PMID 27980775, 2016). "To confirm this T helper phenotype, we performed intracellular cytokine staining (ICS) for Th1 (IFN-γ), Th2 (IL-13), Th17 (IL-17A) and Treg (IL-10) associated cytokines in polyclonally stimulated lung leukocytes on day 7 post-infection." (PMID 27683080, 2016). "IL‐17A‐deficient mice showed a decreased survival rate, and increased bacterial burden in the lungs after the infection when compared to the wild‐type mice." (PMID 27980775, 2016). "In the context of the human airway, interleukin-17A (IL-17A) signaling is associated with severe inflammation, as well as protection against pathogenic infection, particularly at mucosal surfaces such as the airway." (PMID 27723765, 2016). "A TH1/TH17 response is associated with the production of IL-1 and IL-17A to promote abscess formation at the site of infection." (PMID 26580658, 2015). "IL-17A, the hallmark cytokine of the Th17 subset, has been demonstrated to be essential for protection in a number of murine infection models." (PMID 26075052, 2015). "Although IL-17A and IL-22 secretion can be a hallmark of the adaptive phase response to infection, it is becoming increasingly clear that bacterial pathogens trigger rapid IL-17A- and IL-22-dependent innate defense in the gut mucosa." (PMID 25926936, 2015). "Susceptibility to such a narrow spectrum of infections is surprising and indicates that the IL-17 pathway and, in particular, IL-17A and IL-17F play a particular and non-redundant role in host defense against mucocutaneous infections with C. albicans." (PMID 26274976, 2015).